SULF1 (sulfatase 1)
Diseases named in the same sentence as SULF1 in open-access papers (continued):
Sharing a sentence is not in itself a finding about the gene and the disease.
cancer (continued). "The sulfatase family, consisting of sulfatase 1 (SULF1) and sulfatase 2 (SULF2), is involved in multiple physiological and pathological processes by regulating the sulfation status of heparan sulfate proteoglycan, which has become one of the hot spots in cancer research (7, –9)." (PMID 32049100, 2020). "Three enzymes – heparanase, Sulf1 and Sulf2 – play crucial roles in regulating HSPG functioning in this compartment and the up- and down-regulation of these proteins in a large variety of cancers demonstrates how important they are in promoting or repressing malignancy." (PMID 25105093, 2014). "Targeting SULF1 and/or SULF2 could be interesting strategies to develop novel cancer therapies." (PMID 21599997, 2011). "Finally, targeting SULF1 and/or SULF2 could be interesting strategies to develop novel cancer therapies." (PMID 21599997, 2011). "Finally, they demonstrated that curcumin treatment stimulated the expression of tumor suppressor protein SULF1, which could influence multiple tyrosine kinase-signaling pathways, making SULF1 a potential molecular target for MPM and other cancer treatment options." (PMID 34361048, 2021). "We observed >2-fold upregulation of both SULF1 and SULF2 mRNA in four cancer studies from the TCGA (HNSC, ESCA, LUSC, and STAD) and all these cancers remain significantly upregulated compared with the GTEX normal tissues." (PMID 36428645, 2022). "The presence of SULF-1 alternate splicing forms has not yet been confirmed in humans, but it would be logical that a functional isoform could counterbalance or negate the function of the longer HSULF-1 or otherwise contribute to metaplasia in those human cancers over-expressing the isoform." (PMID 22873647, 2012).
infection (4 papers, 2011 to 2023). The state of being infected such as from the introduction of a foreign agent such as serum, vaccine, antigenic substance or organism. "Similar results were obtained for non-infection associated TashAT2 modulated candidates, with higher expression confirmed for sulphatase 1 (SULF1), Lanthionine synthase C-like protein 3 (LANCL3) and troponin (TNNC1)." (PMID 37276213, 2023). "Still, the anti-correlation of NQO1/SULF1 and the low transition probability of cells with high NQO1 levels into infection was observed." (PMID 31653857, 2019).
psychiatric disorder (3 papers, 2021 to 2026). A disorder characterized by behavioral and/or psychological abnormalities, often accompanied by physical symptoms. "It is therefore possible that Sulf1 is associated with appetitive/aversive behaviors, motivation, and integration of sensory information and may have a relation with psychiatric diseases and drug addiction." (PMID 34489650, 2021). "Given sex‐dependent differences in psychiatric disorders in humans, it will be important to examine the effects of Sulf1 disruption in female mice in the future." (PMID 41486756, 2026).
hematologic malignancies (1 paper, 2014). "Association of heparanase, Sulf1, and Sulf2 in solid tumors and hematologic malignancies." (PMID 25105093, 2014).
SULF1 also shares sentences with these, for which no sentence is quoted: astrocytoma (2 papers); CNS cancers (2); idiopathic pulmonary fibrosis (2); ovarian tumors (2); renal carcinoma (2); achondrogenesis type IB (1); adenocarcinoma (1); anaplastic astrocytoma (1); Arteriovenous Malformations (1); Ataxia (1); atelosteogenesis type II (1); benign tumor (1); brain cancer (1); cervical adenocarcinoma (1); cervical intraepithelial neoplasia (1); chlamydia (1); chondrodysplasia (1); clear cell carcinoma (1); colitis (1); colon adenoma (1); colorectal adenoma (1); demyelination (1); depression (1); epidermodysplasia verruciformis (1); Failure to thrive (1); glioblastoma (1); glioma (1); heart failure (1); ischemic stroke (1); kidney failure (1).
A further 14 diseases each share a sentence with SULF1 in 1 paper.